A2MP1 (alpha-2-macroglobulin pseudogene 1 )
Synonyms: A2MP; PZP2P
Gene: Long non-coding RNA gene on chromosome 12 (9,228,533 to 9,234,207, reverse strand). Ensembl gene ENSG00000291190.
Diseases named in the same sentence as A2MP1 in open-access papers:
A2MP1 is named in the same sentence as 4 diseases in open-access papers, as found by Europe PMC text mining. Sharing a sentence is not in itself a finding about the gene and the disease. The quoted sentences say what the papers report.
tendinitis (1 paper, 2022). Inflammation of a tendon, usually resulting from an overuse injury. "LlncRNA-COL6A4P2, A2MP1 and LOC100996671 may regulate the inflammation of LHBT in RCT patients through NFKB2/NF-kappa B signaling pathway, and preliminarily revealed the pathological molecular mechanism of tendinitis of LHBT." (PMID 35725478, 2022).
respiratory diseases (1 paper, 2017). "In addition, given that rs16918212 and the A2MP1 gene have not been associated with lung function impairment or respiratory diseases we think the association is likely not a true finding." (PMID 28073367, 2017).
A2MP1 also shares sentences with these, for which no sentence is quoted: Alzheimer disease (1 paper); Cough (1).